STAT3 (signal transducer and activator of transcription 3)
Diseases named in the same sentence as STAT3 in open-access papers (continued):
Sharing a sentence is not in itself a finding about the gene and the disease.
cancer (continued). "Here, we review the role of STATs in cancers and inflammation while discussing current therapeutic implications in different cancers and test models, especially the delivery of STAT3/5 targeting siRNA using nanoparticulate delivery system." (PMID 30847297, 2019). "Signal transducer and activator of transcription 3 (Stat3) have critical roles in cancer growth and metastasis and have been confirmed as a promising anticancer target." (PMID 31649548, 2019). "As an oncogene and is activated in a wide range of malignant cells, STAT3 is considered to be one of the most important therapeutic targets, particularly, for cancers." (PMID 31293595, 2019). "For example, STAT3 is overexpressed and active in many types of cancer, and its targeting by specific inhibitors is being investigated as a potential cancer treatment." (PMID 31075146, 2019). "STAT3 has two isoforms (α and β), and STAT3α is the most-studied isoform involved in cancer progression." (PMID 31600993, 2019). "Casein kinase 2 (CK2) production, which is considered to be an angiogenic contributor, is also under the auspices of STAT3, both in MDSCs and cancer cells." (PMID 31847487, 2019). "The activation of STAT3 signal transduction in macrophages in response to exosomes obtained from cancer cells was also evaluated." (PMID 31697737, 2019). "Junb is a transcriptional factor that regulates gene expression on multiple levels, but the functionality of this Stat3/Junb interaction deserves future study in relation to cancer cachexia." (PMID 31013615, 2019). "Post-translational modification through reversible methylation of STAT3 by histone-modifying enzymes has been reported in other cancers." (PMID 31130718, 2019). "We also observed an augmented anti-cancer immunity when co-culturing the PBMCs and STAT3 sh cancer cells treated with PD-L1 Ab." (PMID 31511071, 2019). "Given its critical contributions to cancer progression, IL-6 signaling pathway (IL6-/IL6R/JAK/STAT3) is being actively pursued for novel cancer therapies." (PMID 32039001, 2019). "STAT3 is crucial for progression of cancer and promotes cancer stem cells self-renewal and differentiation." (PMID 31581950, 2019). "Recent studies showed that activated STAT proteins, especially STAT3, are involved in the progression of many malignant tumors." (PMID 31186039, 2019). "Debio 0617B demonstrated dose-dependent inhibition of pSTAT3 in STAT3-activated cancer cell lines as well as suppressing cell proliferation in several cancer cell lines and in malignant xenografts derived from patients." (PMID 30847297, 2019). "It is well known that IL-6 can activate the early acute phase response by activating STAT3 (Tyr705) and STAT5 (Tyr694/Tyr699) signaling pathways and plays an important role in diseases associated with chronic inflammation, including cancer development." (PMID 30621055, 2019). "In the last years, many natural SLs able to induce apoptosis through the inhibition of STAT3 signaling have been recognized in different cancer cellular and animal models." (PMID 31781335, 2019). "In some cancer cells, STAT3 is known to escape NK cell immune surveillance by regulating NKG2D ligand expression." (PMID 31212870, 2019). "In some metastatic and cancer stem cells (bladder, colon, lung, and breast carcinomas), phosphorylated STAT3 (pSTAT3) promotes cancer proliferation by upregulating antiapoptotic proteins (BCL-2, BCL-xl), pluripotency markers (OCT4), and proto-oncogenes (MYC)." (PMID 31600993, 2019). "Future perspectives include developing more potent and selective STAT3 inhibitors for cancer therapy." (PMID 31861597, 2019). "It is still feasible that compound 19 interacts with the upstream signaling pathways of STAT3/NF-κB, thereby impacts the cancer stem cell phenotype." (PMID 31360301, 2019). "The findings also demonstrate crucial roles for the 14–3-3ζ/HO-1 complex in the regulation of STAT3 signaling and cancer cell survival." (PMID 30606233, 2019).
cancer (continued). "The compounds OPB-31121, OPB-51602 and OPB-111077, which are substances from Otsuka Pharmaceuticals, were designed to inhibit STAT3 phosphorylation in cancer cell lines and xenograft models by targeting the STAT3 SH2 domain." (PMID 31817042, 2019). "The data presented here provide a mechanistic explanation for the well-documented functional association observed between the STAT3 and PI3K/Akt signaling pathways in cancer." (PMID 30622697, 2019). "Fifty gene sets were identified in common between all four cancer types indicating a unified set of STAT3-related regulatory programs." (PMID 31534498, 2019). "Accumulating evidence has indicated that downregulating STAT3/STAT5 mitigates the malignant behavior of cancer cells, highlighting the potential of STAT3/STAT5 as a therapeutic target." (PMID 31861720, 2019). "Mito-STAT3 activation is mediated by Ser727 phosphorylation and has been shown to be crucial in immunological effector function and in cancer progression." (PMID 31798458, 2019). "This suggests that TGFβ signaling promotes the secretion of IL‐6 from stromal cells, which then induces STAT3 activation in PDA cancer cells." (PMID 31609088, 2019). "Under EGF stimulation, Pyk2, STAT3, and c‐Met interact with each other and form positive feedback, which contributes to prolonging EMT‐associated signals and cancer metastasis." (PMID 31368612, 2019). "As expected, focusing on the subset of 20 pathways containing STAT3, the silenced gene is present in the source set of all of these pathways, except for Pathway in cancer and FoxO signaling that show an empty source set." (PMID 31652275, 2019). "For example, STAT3-induced miR-92a and miR-520d-5p suppression regulate cancer growth and survival, and the inactivation of the phosphorylation of STAT3 decreases miR-155-5p and its anti-cancer properties." (PMID 31737624, 2019). "Our cell sorting data suggest that both NF-κB and STAT3 are activated in the cancer stem cell populations." (PMID 31360301, 2019). "The STAT3 gene, the top identified hub, is a component of essential chemical signaling pathways within cells and an ideal target for chemoprevention and cancer therapy." (PMID 30913233, 2019). "Activation of STAT3 in several cancers contributed towards degradation of ECM, primarily mediated through increased activity of matrix-degrading Matrix Metallo-Proteinases (MMPs)." (PMID 31861720, 2019). "Increasing studies showed that STAT3 is an essential gene that participates in cancer cell proliferation, apoptosis, metastasis, and other cellular events including EMT." (PMID 31186039, 2019). "Signal transducer and activator of transcription 3 (STAT3) is a key element in multiple signaling pathways and is activated aberrantly in many human cancers." (PMID 31143708, 2019). "STAT has dual functions of signal transduction and transcriptional activation, and the abnormal persistent activation of STAT3 signal has been found in human cancer cells." (PMID 30893785, 2019). "Signal transducer and activator of transcription 3 (STAT3) is a transcription factor involved in proliferation, metastasis, and invasion of cancer cells." (PMID 31337063, 2019). "There is strong evidence that STAT3 signaling plays an important role in cancer and more specifically, in HGG tumorigenesis." (PMID 31361777, 2019). "Currently, STAT3 and NF-κB pathways are two major signaling pathways to link inflammation and cancer." (PMID 31650028, 2019). "Taken together, the results clearly show that STAT3 and STAT5 are important cancer genes despite their relatively low mutation frequency." (PMID 31557897, 2019). "In various cell types, including cancer cells and myeloid cells, STAT3 can be induced as an atypical signal transducer of IFN-γ while the interplay between STAT1 and STAT3 determines the biological outcome." (PMID 31406210, 2019). "Associations of STAT3 and STAT5 with cancer progression are well established and heavily studied, and hence, are the main focus of this review." (PMID 31817042, 2019).
cancer (continued). "Activated STAT3/5 proteins target specific inhibitors of apoptosis that mainly act on the intrinsic pathway to suspend cell death in cancer cells." (PMID 31861720, 2019). "Conversely, robust STAT3 signaling activity in M2-TAMs and N2-TANs correlates with the production of factors able to drive cancer cell EMT (OSM, IL-6, TGF-β) and angiogenesis (VEGF, TGF-β, PDGF, and FGF)." (PMID 31684144, 2019). "Among them, STAT3 has been described as an important signaling mediator in malignant diseases by promoting the expression of genes involved in cancer proliferation, cell survival, immune suppression, inflammation, and metastasis." (PMID 31412593, 2019). "New strategies involving vaccination, bispecific mAbs, STAT3 inhibitors and drugs targeting immunosuppression are tested and will probably change the face of pMMR cancer treatments." (PMID 31447840, 2019). "STAT3 signalling has been shown to promote cancer cell migration in response to environmental stimuli." (PMID 30947697, 2019). "Chromatin immunoprecipitation (ChIP) sequencing data from the University of California, Santa Cruz (UCSC) genome browser indicated that STAT3 binds to the IRF9 promoter near the transcription start site in multiple cancer cell lines." (PMID 30679726, 2019). "Pharmaceutical inhibition of Stat3 by Napabucasin—a drug already in Phase II/III clinical trials—significantly abrogated the capacity of CD167a-expressing cancer cells to form lung metastases." (PMID 31086186, 2019). "The current literature points to the important role of HSP90/STAT3/STAT5 in cancer growth and the ability to thwart chemotherapy." (PMID 31861612, 2019). "Further investigations are underway in our laboratory to develop more efficient derivatives, identify its precise target proteins and finally determine clinical potentials of 2-ethoxystypandrone as a cancer stemness STAT3 signaling inhibitor." (PMID 30709346, 2019). "Literatures have shown that over-expression and aberrant activation of STAT3 contributes to the tumorigenesis, progression, and poor prognosis of several cancers including OS47–50." (PMID 31534119, 2019). "In our study, we focused on the STAT3 expression in the glandular epithelium, and distinguished between cancer and benign areas." (PMID 30905090, 2019). "Emerging evidence suggests that abnormal STAT3 signaling drives the initiation and progression of human cancers through the inhibition of apoptosis and driving multiple pro-oncogenic functions." (PMID 31052435, 2019). "The findings that 14–3-3ζ and HO-1 interact in human cancer cells, and that 14–3-3ζ mediates HO-1 stabilization led us to investigate the relative role of each component in regulating STAT3 Tyr705 phosphorylation." (PMID 30606233, 2019). "Within different STAT members, STAT3 is regularly overexpressed in cancer cells and can modulate the expression of various oncogenic genes controlling the growth and metastasis of malignant cells." (PMID 31330969, 2019). "Here, we discuss the impact of microenvironmental signals on STAT3/STAT5 activation during cancer development and progression." (PMID 31684144, 2019). "And it has been reported that overexpression of SMC4 activates JAK2/Stat3 and TGFβ/Smad pathway and promotes aggressiveness of cancer cells." (PMID 31871499, 2019). "In fact, the NF-kB/IL-6/STAT3 pathway plays an important oncogenic role in cancers that arise from chronic inflammation such as HCC." (PMID 31731457, 2019). "In HNSCC cancers, the over-expression of the signal transducer and activator of transcription 3 (STAT3) promoted growth and survival." (PMID 31652849, 2019). "For instance, in pancreatic cancer, stromal HH/GLI signaling has been shown to induce IL6 expression, which in turn results in paracrine activation of STAT3 in the tumor cell compartment, thereby supporting cancer growth and survival." (PMID 31878932, 2019).
cancer (continued). "Collectively, these observations provide evidence that the STAT3 activation pathway is crucial for HPV positive cancer cell proliferation." (PMID 31226168, 2019). "STAT3 is known to mediate cell survival in many cancers, and U266 cell line is reported to have constitutively activated STAT3 pathway." (PMID 31058086, 2019). "Collectively, these data show that 14–3-3ζ regulates the stability of HO-1 to promote cancer cell proliferation and STAT3 signaling activation." (PMID 30606233, 2019). "Hyperactivation of STAT3 via the constitutive phosphorylation of Y705 is common in most human cancers." (PMID 31573734, 2019). "The control molecule, MT STAT3, was largely ineffective against either the cancer cell lines or the NOKs." (PMID 31671769, 2019). "The induction of STAT3 transcriptional activity increases the expression of many genes involved in cancer cell proliferation, survival, migration, invasion, angiogenesis, and metastasis." (PMID 31491838, 2019). "Previous studies have shed light on the role of STAT3 dysregulation in cancer progression and evaluated it as a target for potential therapeutic interventions using genetic manipulation." (PMID 31534498, 2019). "Both HPV16+ and HPV18+ cancer cells retained markedly higher levels of STAT3 phosphorylation at both Y705 and S727 residues compared to the HPV negative cell lines." (PMID 31226168, 2019). "In cancer cells, increased STAT3 activity induces EMT-driving transcription factors, such as ZEB1, SNAIL, and Twist, which initiate the repression of epithelial markers and expression of mesenchymal markers (N-cadherin, Vimentin)." (PMID 31684144, 2019). "NF-κB and STAT3 are two main pro-inflammatory signaling pathways that undoubtedly play major roles in inflammation-driven cancers where their-co-activation has a synergistic effect on expression of oncogenic and pro-inflammatory transcription targets." (PMID 31292446, 2019). "Because xanthatin inhibited the JAK/STAT3 and NF‐κB signalling pathways, we next examined the activation status of the signalling proteins in the two pathways in these cancer cell lines." (PMID 30993883, 2019). "GQ-ODNs have been proposed as a class of unique, anti-cancer STAT3 inhibitors which directly destabilize the homodimerization of STAT3, and thus interfere with its DNA binding activity." (PMID 31671769, 2019). "Agents that suppress the activation of STAT3 reportedly have potential for cancer prevention and treatment." (PMID 31117333, 2019). "Many of the STAT3 upstream kinase inhibitors have demonstrated efficacy in cancer, suggesting a therapeutic window for STAT3-dependent cancer." (PMID 31438567, 2019). "Among these genes, NGFR, PRKN, STAT3, IDH2, etc. were associated with the neuronal system and cancer pathway as the significant terms (P < 0.001)." (PMID 31708732, 2019). "STAT3 activation is therefore tightly regulated at multiple levels to prevent hyperactivation of STAT3-mediated pathologies, including cancers, autoimmune and inflammatory disorders." (PMID 31293595, 2019). "Pro-cancer events activate two major cell signaling pathways: nuclear kappa factor (NFkB) and signal transducer and activator of transcription 3 (STAT3)." (PMID 31211796, 2019). "This correlation sustained in cancer tissues harboring episomal form demonstrated a low level of active STAT3." (PMID 31487312, 2019). "In cancer stem cells, transcription factors selectively activated include signal transducer and activator of transcription 3 (STAT3) and nuclear factor κB (NF-κB)." (PMID 31360301, 2019). "STAT3 phosphorylation followed by irradiation therapy and chemotherapy presents a challenge for cancer treatment since pSTAT3 contributes to the transcription of anti-apoptotic genes including Mcl1, Bcl2, Bcl-xL, and BIRC5." (PMID 31105556, 2019). "IL-6, JAK1, JAK2 and STAT3 which are considered main components of this pathway, have been found to be overexpressed in different cancers, including BCC." (PMID 31342143, 2019).
cancer (continued). "STAT3 transcriptionally regulates expression of a set of downstream genes including c-Myc and Bcl2 in control of tumorigenesis and chemo-resistance in cancer." (PMID 32010177, 2019). "We further found that the exosomes secreted from hypoxic BMSCs increased the cancer cell expression of total and phosphorylated STAT3." (PMID 30866952, 2019). "FDA IND-directed pharmacologic and toxicity studies are planned to enable a Phase I trial of the cyclic STAT3 decoy in cancer patients." (PMID 31671769, 2019). "A previous report revealed that binding of HGF to c-Met triggers receptor homodimerization leading to subsequent promotion of Src/STAT3 signaling and cancer progression." (PMID 30782177, 2019). "The signaling pathway of Janus kinase (Jak)-signal transducer and STAT3 is constitutively activated and abnormally expressed in cancer cells and plays critical roles in cell survival and apoptosis." (PMID 31354479, 2019). "In normal physiological conditions, STAT3 is activated temporarily from a few minutes to several hours; however, in human cancer cells, STAT3 can be constitutively activated." (PMID 31597912, 2019). "In the TME, the STAT3/ROS signaling pathway is activated by growth factors secreted by cancer cells." (PMID 31847487, 2019). "GO analysis revealed an enrichment of a cancer-promoting inflammation program, as characterized by the top GO term ‘secretion by cell’ and ‘positive regulation of tyrosine phosphorylation of Stat3 protein’." (PMID 31735169, 2019). "ISS-610 also demonstrated growth inhibitory activity against several different cancer cell lines characterized by hyperactivation of STAT3." (PMID 31671769, 2019). "The JAK2/STAT3/IL-6 pathway is hyperactivated in several types of cancer and important to the growth of BCSCs." (PMID 31480284, 2019). "To determine the relationship between ITGA2 and the STAT3 signaling pathway, we, first of all, examined the mRNA expression level of STAT3 in cancer cells infected with sh-Control or sh-ITGA2." (PMID 31818309, 2019). "It has been reported that AXT suppresses cancer development targeting the JAK/STAT3 pathway and its downstream target gene expression of MMPs in a hamster model of oral cancer." (PMID 31263239, 2019). "Napabucasin (BBI-608, Boston Biomedical Inc., Cambridge, MA, USA) is an orally available first-in-class cancer stemness inhibitor that appears to target and inhibit gene transcription induced by STAT3 and cancer cell stemness properties." (PMID 30857342, 2019). "Among the STAT proteins, STAT3 and STAT5 are the most strongly implicated in the pathogenesis of cancer." (PMID 31130718, 2019). "STAT3 is known as a downstream factor from rapamycin (mTOR) and a regulator of HKII; thus, the mTOR–STAT3–HKII pathway is an interesting target for glycolysis inhibition in cancer cells." (PMID 31261935, 2019). "As a transcriptional factor, STAT3 can drive the expression program of a plethora of protein factors, some of which are essential for many metabolic pathways in cancer cells." (PMID 31500219, 2019). "Other protein phosphatases mutated in cancer, e.g., PTPRD, also negatively regulate STAT3 activation." (PMID 31844068, 2019). "We summarize the development of inhibitors against the SH2 domains of STAT3/5 and discuss their applicability as cancer therapeutics." (PMID 31817042, 2019). "The related compound, brevilin A, has been reported to decrease the expression of p-STAT3 in many types of cancers, including lung, breast, and liver." (PMID 31108969, 2019). "Constitutively, the activation of STAT3 is well known to play an essential role in the development of multiple cancers, including OSCC, where its hyper-activation up-regulates the transcription of cyclin D1, survivin, and Bcl-xL." (PMID 31315217, 2019). "Napabucasin (BBI608) is the most extensively investigated STAT3-targeted agent against cancers thus far." (PMID 31731457, 2019).